RNU2-47P (RNA, U2 small nuclear 47, pseudogene)
Gene: Small nuclear RNA gene on chromosome 9 (12,300,266 to 12,300,451, reverse strand). Ensembl gene ENSG00000222581.
Homologues: Orthologues: chimpanzee U2 (95% identical), macaque U2 (86% identical), pig U2 (75% identical), dog U2 (68% identical), guinea pig U2 (62% identical), rat LOC120096853 (42% identical). Paralogues in human: RNU2-36P (77% identical), RNU2-2 (76% identical), RNU2-14P (75% identical), RNU2-32P (75% identical), RNU2-62P (74% identical), U2 (74% identical), RNU2-59P (73% identical), RNU2-23P (73% identical), RNU2-39P (73% identical), RNU2-6P (73% identical), U2 (73% identical), RNU2-26P (72% identical), and 66 more.